SOX9 (SRY-box transcription factor 9)
Diseases named in the same sentence as SOX9 in open-access papers (continued):
Sharing a sentence is not in itself a finding about the gene and the disease.
Hydrocephalus (1 paper, 2023). Hydrocephalus is an active distension of the ventricular system of the brain resulting from inadequate passage of CSF from its point of production within the cerebral ventricles to its point of absorption into the systemic circulation. "G9a inactivation in neural crest cells using Wnt1-Cre or Sox9-Cre altered proliferation and differentiation of cranial bone cells and decreased ossification of the frontal bones, but did not cause hydrocephalus." (PMID 37470706, 2023).
hyperhomocysteinemia (1 paper, 2020). A serious metabolic condition caused by mutations in the MTHFR gene, medications, or nutritional deficiency. "Hyperhomocysteinemia and hyperuricemia both could cause an induction of SOX9 expression." (PMID 32338289, 2020).
hypophosphatemia (1 paper, 2010). Lower than normal levels of phosphates in the circulating blood. "Based on Sox9 and Sox5 mRNA levels, neither the initial recruitment of cells to the callus nor their lineage commitment was effected by hypophosphatemia." (PMID 19839770, 2010).
inflammatory bowel disease (1 paper, 2025). A spectrum of small and large bowel inflammatory diseases of unknown etiology. "in the Intestinal tissues of patients with inflammatory bowel disease (IBD), including Crohn’s disease, and as well as in conditions such as Sjögren’s syndrome abnormalities in SOX9 expression are frequently noted." (PMID 41293317, 2025).
insulinoma (1 paper, 2022). "In Group A, 4 from 17 samples (three NETG3s and one NETG2 (an insulinoma and a MEN1 syndrome tumor)) displayed staining for SOX9, albeit with a low and heterogenous pattern, unlike Group B positive tumors." (PMID 35227293, 2022).
intestinal cancer (1 paper, 2017). "ELP3 is induced by Wnt signaling and promotes SOX9 translation, which is necessary for maintenance of intestinal cancer stem cells 38, and SOX9 is upregulated in stem cell population in tongue SCC cells." (PMID 28834425, 2017).
intestinal polyposis (1 paper, 2025). "We aged animals for 120 days to establish a pan-intestinal polyposis phenotype and then induced recombination with a single pulse of tamoxifen to activate YFP expression in Sox9(+) cells." (PMID 40467544, 2025).
intraepithelial carcinoma (1 paper, 2023). "In this study, SOX9 expression levels were elevated in atypical invasive urothelial and intraepithelial carcinomas." (PMID 38002064, 2023). "In this study, we investigated the expression of SRY-box transcription factor 9 (SOX9) in highly atypical invasive urothelial and intraepithelial carcinoma and identified miRNAs involved in cancer cell growth and invasion using SOX9 as a target molecule." (PMID 38002064, 2023). "High-grade invasive urothelial and intraepithelial carcinomas with high SOX9 expression were poorly differentiated tumors, suggesting that tumor cells have acquired diversity and are capable of various differentiations as a result of enhanced transcription factor function." (PMID 38002064, 2023). "Although most non-invasive and non-muscle layer invasive urothelial carcinoma tissues showed negative or weakly positive intensity, SOX9 levels were significantly upregulated in muscle invasive urothelial carcinoma and carcinoma in situ." (PMID 38002064, 2023).
liposarcoma (1 paper, 2025). A usually painless malignant tumor that arises from adipose tissue. "This study aimed to investigate the gene expression profiles of SOX9, GATA3, and GATA4 in liposarcoma subtypes and to assess their associations with clinicopathological parameters." (PMID 41303462, 2025). "Their predicted involvement in SOX9 regulation supports its potential contribution to inflammation-driven or stress-responsive signaling cascades in liposarcoma." (PMID 41303462, 2025). "Notably, although SOX9, GATA3, and GATA4 have been previously implicated in various malignancies, this is the first qRT-PCR-based study to systematically quantify their expression in human liposarcoma tissue." (PMID 41303462, 2025). "This study provides qRT-PCR-based evaluation of SOX9, GATA3, and GATA4 gene expression in liposarcomas, revealing consistent overexpression patterns across multiple histological subtypes." (PMID 41303462, 2025). "Despite progress in molecular diagnostic tools, the current literature offers limited data regarding the expression profiles of transcription factors such as the Sex-determining region Y-box 9 (SOX9), GATA3, and GATA4 in liposarcoma." (PMID 41303462, 2025). "In this study, we conducted a comprehensive molecular analysis of SOX9, GATA3, and GATA4 gene expression in a cohort of 42 liposarcoma cases using quantitative real-time PCR." (PMID 41303462, 2025). "The relative expression values (RQ) of SOX9, GATA3, and GATA4 were evaluated in 42 liposarcoma cases." (PMID 41303462, 2025). "Considering these knowledge limitations, the present study aims to evaluate the relative expression levels (RQ) of SOX9, GATA3, and GATA4 in a series of human liposarcoma samples, using a comparative molecular approach based on quantitative real-time PCR." (PMID 41303462, 2025). "To assess the prognostic relevance of SOX9, GATA3, and GATA4 gene expression levels on overall survival in liposarcoma patients, we performed univariate Cox proportional hazards regression using continuous RQ values as covariates." (PMID 41303462, 2025). "An important and somewhat counterintuitive observation in our dataset was the frequent overexpression of SOX9 and GATA4 in ALT/WDLS cases, which are classically regarded as low-grade or well-differentiated liposarcoma subtypes." (PMID 41303462, 2025). "Boxplot analysis confirmed substantial interindividual variability in the expression levels of SOX9, GATA3, and GATA4 across the 42 analyzed liposarcoma cases." (PMID 41303462, 2025). "Together, these data justify investigating SOX9, GATA3, and GATA4 within the mesenchymal context of liposarcoma, where they may cooperatively contribute to aberrant lineage maintenance and tumor progression." (PMID 41303462, 2025). "Collectively, these findings underscore that the altered expression of SOX9, GATA3, and GATA4 observed in liposarcoma may reflect dysregulated MSC differentiation mechanisms and impaired adipogenic transcriptional control." (PMID 41303462, 2025). "This raises the possibility that SOX9, GATA3, and GATA4 are not merely subtype-specific markers but may instead reflect a broader oncogenic pathway active across diverse liposarcoma variants." (PMID 41303462, 2025).
liver cirrhosis (1 paper, 2023). "In summary, we found ACTB, TAGLN, VIM and SOX9 are the potential key biomarkers of liver cirrhosis." (PMID 36725885, 2023).
malignant glioma (1 paper, 2021). A grade III or grade IV glioma arising from the central nervous system. "SOX9 is strongly expressed in malignant gliomas and its upregulation is associated with higher tumor grade and worse survival outcomes." (PMID 34012965, 2021). "In a mouse model of malignant glioma, codeletion of SOX9 and POU3F2 regulatory enhancer elements in the nuclear factor IA (NFIA) locus block NFIA expression and inhibit tumorigenesis." (PMID 34012965, 2021).
mitral valve diseases (1 paper, 2024). "Mutations in a variety of genes that are responsible for encoding structural proteins, signaling molecules, and transcription factors—namely FBN1, FLNA, MMP2, and SOX9—have been identified as significant contributors to the pathology of mitral valve diseases." (PMID 39273357, 2024).
myxoid chondrosarcoma (1 paper, 2026). A chondrosarcoma characterized by the presence of myxoid changes. "Immunohistochemically, cytokeratin was negative and SOX9 was diffusely positive, raising suspicion for extraskeletal myxoid chondrosarcoma." (PMID 42294281, 2026).
myxoma (1 paper, 2024). A benign soft tissue neoplasm characterized by the presence of spindle and stellate cells, lobulated growth pattern, and myxoid stroma formation. "Myxoma cells derived from myxoma were found to be independent of normal heart tissue and formed a distinct subset in the integrated profile, with high expression of the myxoma cell marker such as PDE3A and the transcription factor SOX9, which regulate cell differentiation." (PMID 39090109, 2024).
neoplasm of the bile ducts (1 paper, 2025). "The regions showing neoplasm of the bile ducts showed nuclear TFEB, TFE3, and SOX9, and hyperactivation of mTORC1 as evidenced by immunostaining for the phosphorylated S6 protein of the 40S ribosomal subunit (P-S6), used as readout of mTORC1 activity." (PMID 40189703, 2025).
OI type V (1 paper, 2024). "Disruptions to osteo-chondroprogenitor cell differentiation due to activated ERK/SOX9 signaling contributes to the abnormal skeletal development in osteogenesis imperfecta type V." (PMID 38885336, 2024).
oral squamous cell carcinoma (1 paper, 2025). "This is the first publication, to our knowledge, regarding this topic in the field of oral squamous cell carcinoma showing a group of patients with poorer overall survival by representing a distinct expression pattern of SOX2 and SOX9." (PMID 39180200, 2025).
orofacial cleft (1 paper, 2021). A disorder of facial skeleton that is characterized by cleft lip and/or cleft palate that result in feeding, speech and hearing problems caused by failures during development. "To show that TGFβ1 increase can affect downstream genes associated with orofacial clefts, we looked at expression of SOX9 transcription factor." (PMID 33577554, 2021). "Expression of another SOXE transcription factor group member associated with orofacial clefts, SOX10, is not altered upon topiramate treatment, showing specificity for SOX9 upregulation." (PMID 33577554, 2021).
ovarian hyperstimulation syndrome (1 paper, 2025). A complication of ovulation induction in infertility treatment. "Similarly, EGR1 was found to promote ovarian hyperstimulation syndrome through increasing SOX9 expression." (PMID 39665647, 2025).
Pallister Killian syndrome (1 paper, 2014). "Among the differentially expressed genes, we identified several genes whose misexpression may be associated with the clinical phenotype of Pallister Killian syndrome such as downregulation of ZFPM2, GATA6 and SOX9, and overexpression of IGFBP2." (PMID 25329894, 2014).
pancreatic diseases (1 paper, 2022). "In pancreatic diseases, SOX9 accelerates acinar-to-ductal metaplasia and has a critical role." (PMID 35884771, 2022).
papillary thyroid cancer (1 paper, 2024). "Knockout of SOX9 has been demonstrated to inhibit the proliferative EMT process of papillary thyroid cancer cells by inhibiting the Wnt/β‐catenin signaling pathway." (PMID 40626133, 2024).
Patent foramen ovale (1 paper, 2018). Failure of the foramen ovale to seal postnatally, leaving a potential conduit between the left and right cardiac atria. "In humans, mutations upstream and within SOX9 have been linked to congenital heart and vessel defects including Tetralogy of Fallot, ventricular and atrial septal defects, patent foramen ovale, and aortic stenosis." (PMID 30224706, 2018).
Peritoneal Fibrosis (1 paper, 2018). Disorder characterized by a wide range of structural changes in PERITONEUM, resulting from fibrogenic or inflammatory processes. "The role of Sox9 in regulating MMT and peritoneal fibrosis warrants further investigation." (PMID 29774544, 2018).
pituitary adenomas (1 paper, 2021). "Also, it might provide shreds of evidence regarding the possibility of SOX9 involvement in pituitary adenoma tumor formation that can delineate the GH-secreting pituitary adenoma underlying molecular mechanism." (PMID 33736633, 2021). "SOX9 as a regulatory transcriptional mediator affects normal and tumor cell growth with an undefined role in pituitary adenomas pathogenesis." (PMID 33736633, 2021). "In our study, no specific differences were observed in the level of SOX9 expression in male and female participant’s tumor tissues although the correlation of SOX9 with gender in pituitary adenomas can be clarified by further studies." (PMID 33736633, 2021). "Even though pituitary adenomas account as benign and slow-growing tumors, while the expression profile of SOX9 in these tumors obeys the same pattern as SOX9 demonstrated in more malignant solid tumors such as lung and prostate." (PMID 33736633, 2021). "The difference in the SOX9 protein expression level between macro and micro-GH-secreting pituitary adenoma was statistically significant (P < 0.0001)." (PMID 33736633, 2021). "The difference in the SOX9 protein expression level between GH-secreting invasive and non-invasive pituitary adenoma was statistically significant (P = 0.009)." (PMID 33736633, 2021). "Our study provides first data regarding the status of SOX9 as an appealing marker in patients with GH-secreting pituitary adenoma." (PMID 33736633, 2021). "Based on data, the SOX9 protein level was significantly correlated with the SOX9 gene expression level in the subgroup of macroadenoma, microadenoma, and non-invasive GH-secreting pituitary adenoma." (PMID 33736633, 2021). "However, based on the nature of pituitary adenoma tumors which are mainly benign and the limited number of participants with invasive tumors in our study, extending and investigating the role of SOX9 in GH-producing pituitary adenoma tumorigenesis in more diverse patients are recommended." (PMID 33736633, 2021). "The presence and overproduction of SOX9 as a pivotal stem cell marker in GH-secreting pituitary adenoma may highlight the effective impact of stem cells in the pituitary gland which might facilitate organ regeneration also cell differentiation to hormone-secreting cells." (PMID 33736633, 2021). "Based on data presented here, the correlation of age with SOX9 tumor expression was not significant in GH- secreting pituitary adenoma patients." (PMID 33736633, 2021).
polycystic ovary syndrome (1 paper, 2025). A disorder that manifests as multiple cysts on the ovaries. "In polycystic ovary syndrome (PCOS), AMH levels are significantly higher due to an increased number of granulosa cells (GCs) and enhanced transcriptional activity mediated by Foxl2, Sox9, and Gata4." (PMID 40724853, 2025).
polyposis (1 paper, 2025). "Although the resultant phenotype was less profound than in the germline Vil1-Grem1 model, all Villin-CreERT2;Rosa26Grem1 animals developed polyposis with the initial establishment of ectopic crypts on the villi containing aberrantly proliferating Sox9(+) stem/progenitor cells." (PMID 40467544, 2025).
preeclampsia (1 paper, 2023). Preeclampsia is a hypertensive disorder of pregnancy that is characterized by new-onset hypertension with proteinuria presenting after 20 weeks of gestation, and depending on mild or severe forms may initially present with severe headache, visual disturbances, and hyperreflexia. "Hif-1α and SOX9 proteins can be used as a marker to show severity of preeclampsia and regulation of cell proliferation and angiogenesis during placental development." (PMID 37878989, 2023). "Therefore, Hif-1α signal and SOX9 transformation factor may play an important role in determining the severity of preeclampsia and also in the regulation of cell proliferation and angiogenesis." (PMID 37878989, 2023).
prostate hyperplasia (1 paper, 2013). "Increased Sox9 expression is observed at early stages of prostate hyperplasia and is associated with progression to high grade PIN lesions." (PMID 23786676, 2013).
psoriasis (1 paper, 2013). An autoimmune condition characterized by red, well-delineated plaques with silvery scales that are usually on the extensor surfaces and scalp. "We first determined Sox9 expression in psoriasis, a multisystemic disease characterized by hyperproliferation and altered differentiation of keratinocytes." (PMID 23349860, 2013). "In addition, several skin diseases including psoriasis, BCC, KA and SCC, which are related to disturbance of cell growth control, showed higher expression of Sox9." (PMID 23349860, 2013).
renal hypoplasia (1 paper, 2021). Renal hypoplasia is a developmental anomaly in which one or both kidneys (unilateral or bilateral renal hypoplasia, respectively) have a deficit in the number of nephrons and may be small. "It was found that the deletion of Sox8 and Sox9 during renal embryonic development led to renal hypoplasia in mice." (PMID 34215331, 2021).
rosacea (1 paper, 2021). A chronic erythematous skin disorder that affects the face. "Based on the ol-DEGs, we revealed the TF regulatory network in AD/rosacea, indicating a central role of the 24 TFs in regulating the pathogenesis of AD and rosacea, including PPARG, STAT4, sox9, and RORA." (PMID 34899707, 2021).
schistosomiasis (1 paper, 2025). An infectious disease caused by parasitic trematodes of the genus Schistosoma that colonize human blood vessels and release eggs that can cause granulomatous reactions leading to acute (swimmer's itch or acute schistosomiasis syndrome) or chronic disease. "In the ongoing search for anti-fibrotic therapies, targeting SOX9 may be successful in treating fibrosis associated with schistosomiasis and other diverse aetiologies." (PMID 40489560, 2025). "Alongside our previous studies, this suggests a pro-fibrotic role for SOX9 across injury immunotypes and indicates factors downstream of SOX9 may yield therapeutic targets against fibrosis and to promote corrective repair during schistosomiasis and in other fibrotic diseases." (PMID 40489560, 2025).
schwannoma (1 paper, 2015). A benign, usually encapsulated slow growing tumor composed of Schwann cells. "HDF-a showed cytoplasmic immunostaining for the neural-crest and immature Schwann cell marker SOX9, although it is a nuclear marker, as shown in the rat schwannoma cell line." (PMID 26678612, 2015).
sebaceous gland tumours (1 paper, 2020). "This is in accordance with our previous studies on Sox9 immunohistochemical expression in different canine tumours types, including sebaceous gland tumours." (PMID 32397255, 2020).
septal defects (1 paper, 2022). "Using a mouse model in which Sox9 is conditionally deleted from the SHF we demonstrate that in this model virtually all mouse embryos develop septal abnormalities, including complete atrioventricular septal defects (cAVSDs) and isolated ventricular septal defects." (PMID 36354775, 2022).
serous endometrial adenocarcinomas (1 paper, 2021). "The SOX9+LGR5+ signature is stronger in tumors characterized by high copy number (copy-number-high) alterations (Wilcoxon text, P value 6.72 × 10−13), typical of serous endometrial adenocarcinomas and linked with a worse prognosis." (PMID 34857954, 2021).
serous ovarian cancer (1 paper, 2025). "The transcription factor SOX9 is sufficient to induce a stem-like transcriptional state and significant resistance to platinum treatment in high-grade serous ovarian cancer." (PMID 41031891, 2025).
silicosis (1 paper, 2025). Silicosis is a respiratory disease caused by breathing in (inhaling) silica dust. "During the early inflammatory phase of silicosis, SOX9 and SOX2 were re-expressed in the distal lung and exhibited abnormal distribution." (PMID 39974732, 2025). "In the silica-treated mouse model of silicosis, researchers found that SOX9 and SOX2 are markers of embryonic lung stem/progenitor cells." (PMID 39974732, 2025). "However, in the later stages of silicosis, SOX9’s expression level decreased and was unrelated to the progression of fibrosis, indicating that SOX9 could be important in regulating fibrosis during the development of silicosis." (PMID 39974732, 2025).
skin adnexal tumors (1 paper, 2024). "The identification of reliable IHC markers such as CK19 and Sox9 adds to the diagnostic toolkit for veterinarians, allowing for a more accurate differentiation of skin adnexal tumors, including rare neoplasms like EMPSGC." (PMID 39765541, 2024).